DUS4L (dihydrouridine synthase 4 like)
Description:
Catalyzes the synthesis of dihydrouridine, a modified base found in the D-loop of most tRNAs.
Synonyms: PP35; DUS4
Tractability: PROTAC: ubiquitination databases record sites on it.
Gene: Protein-coding gene on chromosome 7 (107,563,484 to 107,579,483, forward strand). Ensembl gene ENSG00000105865.
Subcellular location (Human Protein Atlas): Cytosol
Gene Ontology:
Molecular function: tRNA dihydrouridine synthase activity; tRNA-dihydrouridine20b synthase activity; flavin adenine dinucleotide binding; tRNA-dihydrouridine20a synthase activity
Biological process: tRNA dihydrouridine synthesis; tRNA processing
Genetic constraint (gnomAD): Loss-of-function variants: 29 observed, 33.57 expected, observed/expected ratio (o/e) 0.86, 90% interval 0.64 to 1.18. The upper end of that interval is the gene's LOEUF score, 1.18, which puts it in group 5 of 6, group 1 being the genes least tolerant of losing a copy. Missense variants: 365 observed, 399.01 expected, observed/expected ratio (o/e) 0.91, 90% interval 0.84 to 1. Synonymous variants: 103 observed, 125.41 expected, observed/expected ratio (o/e) 0.82, 90% interval 0.7 to 0.97.
Homologues: Orthologues: chimpanzee DUS4L (100% identical), dog DUS4L (94% identical), guinea pig DUS4L (93% identical), rabbit DUS4L (93% identical), pig DUS4L (91% identical), mouse Dus4l (90% identical), rat Dus4l (90% identical), macaque BCAP29 (80% identical), zebrafish dus4l (67% identical), Caenorhabditis elegans C45G9.2 (44% identical), Drosophila melanogaster Dus4 (42% identical). Paralogues in human: DUS1L (34% identical), DUS2 (29% identical), DUS3L (23% identical).
Diseases named in the same sentence as DUS4L in open-access papers:
DUS4L is named in the same sentence as 3 diseases in open-access papers, as found by Europe PMC text mining. Sharing a sentence is not in itself a finding about the gene and the disease.
DUS4L shares sentences with these, for which no sentence is quoted: cancer (2 papers); hand osteoarthritis (1); knee osteoarthritis (1).